UGT1A1 (UDP glucuronosyltransferase family 1 member A1)
Diseases named in the same sentence as UGT1A1 in open-access papers (continued):
Sharing a sentence is not in itself a finding about the gene and the disease.
Hyperbilirubinemia (continued). "The objective of this study is to elucidate the role of polymorphism in the UGT1A1 in Neonatal Hyperbilirubinemia in Bengkulu, Indonesia." (PMID 29534743, 2018). "In recent years, more and more reports have cast light on the relationship between UGT1A1 polymorphism and severe hyperbilirubinemia, recommending that it is crucial to explore the pathogenesis in the gene level." (PMID 28662083, 2017). "Loss of function alleles in the UGT1A1 gene are associated with drug-related hyperbilirubinemia; carriers of this variant treated with the PI atazanavir develop more severe hyperbilirubinemia, since atazanavir acts as an inhibitor to UGT1A1." (PMID 29577081, 2017). "Montelukast and Disulfiram were sel﻿ected as potentially clinically applicable drug﻿s and tested to reduce serum unconjugated bilirubin (UCB) levels in the Ugt1a1-deficient rat, a model for chronic unconjugated hyperbilirubinemia." (PMID 28490767, 2017). "Because bilirubin is solely glucuronidated by UGT1A1, genetic deficiency in the UGT1A1 gene can result in an onset of severe hyperbilirubinemia (>20 mg/dL serum bilirubin) in humans." (PMID 27822186, 2016). "Several antiretrovirals such as atazanavir and indinavir are associated with unconjugated hyperbilirubinemia secondary to UGT1A1 inhibition comparable to that which occurs in Gilbert's syndrome." (PMID 27065862, 2016). "G6PD deficiency, short HO-1 promoter GT-repeat and GA at nt211 in UGT1A1 are risk factors of neonatal hyperbilirubinemia." (PMID 27557546, 2016). "We show G6PD deficiency, GA at nt211 in UGT1A1, and short HO-1 promoter GT-repeat possess great risks for neonatal hyperbilirubinemia." (PMID 27557546, 2016). "Our study demonstrated that GA at nt211 in UGT1A1 is associated with neonatal hyperbilirubinemia, which is consistent with a number of previous reports." (PMID 27557546, 2016). "Knockout of Ugt1a1 in mice causes very severe hyperbilirubinemia (>15 mg/dL serum bilirubin), which is lethal within 11 days of birth due to the development of kernicterus." (PMID 27822186, 2016). "The data showed 3 gene variants – including G6PD deficiency, GA at nt211 in UGT1A1, and short HO-1 promoter GT-repeat – carried great risks for hyperbilirubinemia." (PMID 27557546, 2016). "Bilirubin is known to have anti-atherosclerotic properties, and multiple studies have shown that individuals with Gilbert’s syndrome, a genetic deficiency in UGT1A1 resulting in a chronic low level hyperbilirubinemia, have a reduced risk for CV events." (PMID 27643691, 2016). "Taken together, the TA7 repeat variant of UGT1A1 (UGTA*28) seems to have a protective effect on hyperbilirubinemia development in Asia neonates." (PMID 26146841, 2015). "Our results revealed that two independent genetic variants in the promoter and coding region of UGT1A1 genes had a substantial impact on the risk of neonatal hyperbilirubinemia." (PMID 26146841, 2015). "Gilbert’s syndrome (GS) is a very common cause of unconjugated hyperbilirubinemia associated with UGT1A1 mutations." (PMID 26107955, 2015). "Our results confirmed the strong association of UGT1A1*6 with the incidence and severity of hyperbilirubinemia." (PMID 26146841, 2015). "The investigation of UGT1A1 showed that rs4148323 (211G>A, Gly71Arg), located in the first exon, was a risk factor in neonatal hyperbilirubinemia, and was associated with higher peak TcB during hospitalization stay." (PMID 25102181, 2014). "In a recent study, hyperbilirubinemia in patients receiving an ATV-based regimen was significantly associated with UGT1A1 rs887829 T allele, higher baseline bilirubin levels and slower plasma ATV clearance." (PMID 25409506, 2014). "We identified a compound heterozygous mutation, p.G71R/p.F170-/p.Y486D, in UGT1A1 gene in an 8-month-old Chinese boy with intermittent hyperbilirubinemia who was clinically diagnosed as CNS-II." (PMID 25319636, 2014).
Hyperbilirubinemia (continued). "In this paper, we found the boy with unconjugated hyperbilirubinemia had a compound heterozygous mutation consisted of three mutations in the UGT1A1 gene (p.G71R, p.F170- and p.Y486D)." (PMID 25319636, 2014). "Uridine Diphosphate Glucuronosyl Transferase 1A1 (UGT1A1) is the key enzyme for bilirubin conjugation while unconjugated bilirubin is the main cause of hyperbilirubinemia." (PMID 25102181, 2014). "Our goal is liver directed gene therapy for Crigler-Najjar syndrome type I, inherited severe unconjugated hyperbilirubinemia caused by UGT1A1 deficiency." (PMID 24386104, 2013). "In our previous study, we found that the UGT1A1 211G > A mutation is associated with neonatal hyperbilirubinemia in Asians." (PMID 24090270, 2013). "Gilbert's syndrome is such a confounder, where the UGT1A1 gene allele *28 has been shown to increase the risk of hyperbilirubinemia with some PI-based treatments." (PMID 23224752, 2013). "The G71R polymorphism, which is common in East Asia, is a risk factor for hyperbilirubinemia and has been associated with an approximate 40% reduction of UGT1A1 activity." (PMID 23388413, 2013). "For example, a common missense mutation at position 211 in exon one of UGT1A1 has been consistently associated with significant and persistent hyperbilirubinemia in neonates of East Asian ethnicity, but is relatively rare in Caucasian or African populations." (PMID 21513526, 2011). "Common variants in UGT1A1 have long been thought to influence the occurrence of severe physiological hyperbilirubinemia in neonates; however, the multifactorial nature of the disorder has made it difficult to decipher this relationship." (PMID 21513526, 2011). "The UGT1A1*28 (promoter (TA)6TAA to (TA)7TAA) is a common genetic variant reducing UGT1A1 activity associated with irinotecan toxicity and hyperbilirubinaemia." (PMID 18547414, 2008). "Impressive lifelong correction of hyperbilirubinemia has been also reported in the Gunn rats following a single intravenous injection of HDAd vector encoding UGT1A1 with negligible chronic toxicity." (PMID 19490653, 2008). "Additionally, the influence of variations in genes encoding for these enzymes on hyperbilirubinemia has been elucidated, and variations of the UGT1A1 Gly71Arg or UGT1A1 TATA promoter are associated with an increased risk of neonatal hyperbilirubinemia." (PMID 37371159, 2023). "Some investigators have found that the UGT1A1 gene is a dominant genetic determinant of bilirubin concentration and that the UGT1A1*28 genotype is associated with an increased likelihood of hyperbilirubinemia and shows different features of association among different races." (PMID 36627697, 2023). "Previously, using a candidate gene approach, Kishi et al3 identified the UGT1A1 promoter TA repeat variant (rs8175347) as associated with hyperbilirubinemia during all treatment phases in a single-institution study at St Jude Children’s Research Hospital (Total XIIIB protocol)." (PMID 36580335, 2022). "Moreover, homozygous carriers of the UGT1A1*28 allele appear to be predisposed to severe hyperbilirubinemia; this risk is intermediate in UGT1A1*28 heterozygotes." (PMID 35745658, 2022). "Moreover, other studies demonstrate that UGT1A1*28 polymorphism is associated with hyperbilirubinemia in newborns." (PMID 35629166, 2022). "UGT1A1*6 mutations and hyperbilirubinemia often occur concurrently." (PMID 35340156, 2022). "In addition, logistic regression indicated that exon mutation (c.211 and /or c.1091) in UGT1A1 gene was associated with increased risk of hyperbilirubinemia in both Han and Uighur neonates." (PMID 36520959, 2022). "In addition, the UGT1A1*6 allele is associated with an increased risk of hyperbilirubinemia in Thai HIV-infected patients treated with indinavir." (PMID 35176049, 2022). "Moreover, UGT1A1 combination was significantly increases the risk of hyperbilirubinemia (P = 0.005)." (PMID 35501760, 2022).
Hyperbilirubinemia (continued). "Similarly, two retrospective analyses of phase II/III studies reported a significant association between UGT1A1*28 homozygotes and hyperbilirubinemia risk with pazopanib." (PMID 33805415, 2021). "Prescribing drugs that inhibit UGT1A1 to patients carrying UGT1A1 loss of function alleles may increase the risk of hyperbilirubinemia and liver toxicity." (PMID 33805415, 2021). "Additionally, patients with both elevated ALT and hyperbilirubinemia were analyzed for HLA-B*57:01 and UGT1A1 variants." (PMID 33805415, 2021). "Specifically, UGT1A1*28 homozygotes may have a higher risk for pazopanib or nilotinib-induced hyperbilirubinemia." (PMID 33805415, 2021). "Similarly, the inhibition of UGT1A1 by pazopanib or nilotinib has been reported to exacerbate hyperbilirubinemia in patients harboring UGT1A1 genetic polymorphisms." (PMID 33805415, 2021). "However, the innate variants of the UGT1A1 gene are under-diagnosed in neonates and under-recognized as a cause of severe hyperbilirubinemia clinically." (PMID 34074250, 2021). "Hence, for the prevention and treatment of hyperbilirubinemia and other UGT1A1-associated human diseases, it was necessary as well as challenging to find some promising UGT1A1 inducers that possess good safety profiles and drug-likeness properties." (PMID 33628187, 2020). "Potential pleiotropic effects of our UGT1A1 SNP (rs6431625) cannot be excluded, and pathways other than mild hyperbilirubinemia associated with lower UGT1A1 activity could therefore also play a role in CRC development." (PMID 32878631, 2020). "Therefore, it is highly desirable to find more efficacious UGT1A1 inducers as novel anti-hyperbilirubinaemia agents for the treatment of UGT1A1-associated human diseases and drug-induced liver toxicity." (PMID 33628187, 2020). "The pathogenic mechanism of hyperbilirubinemia may be related to the inhibition of uridine diphosphate-glucuronosyltransferase (UGT1A1) activity." (PMID 32899072, 2020). "Therefore, we evaluated the role of UGT1A1 in this meta-analysis (c.-3279 T > G) gene polymorphism in neonatal hyperbilirubinemia susceptibility." (PMID 33158427, 2020). "Hyperbilirubinemia is a common complication of nilotinib therapy, whose pathogenic mechanism may be related to the inhibition of UGT1A1 activity." (PMID 32899072, 2020). "Nilotinib-induced hyperbilirubinemia associated with UGT1A1 activity." (PMID 32899072, 2020). "The results indicate that mild hemolysis indeed, exists in a portion of patients with GS and might serve as an important contributor to unconjugated hyperbilirubinemia in addition to UGT1A1 polymorphism." (PMID 32049823, 2020). "In fact, inhibitory effects towards UGT1A1 were reported for silybin, a major flavonoid constituent of milk thistle extract; indeed, the therapy with this substance has also been associated with marked unconjugated hyperbilirubinemia." (PMID 30891115, 2019). "However, even in Gilbert’s syndrome, associated with SNPs in the UGT1A1 gene and a mild hyperbilirubinemia, a lower incidence of cardiovascular diseases has been reported." (PMID 30621171, 2019). "Therefore, we performed a meta-analysis to evaluate the association between the UGT1A1*28 allele and the associated hyperbilirubinemia risk." (PMID 30962262, 2019). "An exome-wide association study demonstrated that UGT1A1 intronic variations may also reduce UGT1A1 enzyme activity and cause unconjugated hyperbilirubinemia." (PMID 31737051, 2019). "ORs and 95% CIs for unconjugated hyperbilirubinemia associated with UGT1A1 haplotypes." (PMID 31737051, 2019). "Pyrosequencing of UGT1A1*28/*6 gene polymorphisms could thus be used as an effective auxiliary method for GS diagnosis after excluding other possible causes of indirect hyperbilirubinemia." (PMID 29386646, 2018).
Hyperbilirubinemia (continued). "In contrast to previous findings, our study found a relatively high incidence of UGT1A1*6 mutation in Bengkulu Indonesian population in both hyperbilirubinemia and normal bilirubin neonate, compared to the frequency in other populations (0.3 and 0.32 respectively)." (PMID 29534743, 2018). "Two inhibitors that could potentially be applied in a clinical setting were selected for subsequent testing in vivo in the Ugt1a1-deficient Gunn rat, an animal model for inherited severe unconjugated hyperbilirubinemia." (PMID 28490767, 2017). "However, in vivo administration of Montelukast did not result in a decrease of serum bilirubin, while Disulfiram appeared to be hepatotoxic to the Ugt1A1-deficient Gunn rat, the animal model for hereditary unconjugated hyperbilirubinemia." (PMID 28490767, 2017). "In the present work, UGT1A1 was screened for gene mutations in 95 Chinese patients with unconjugated hyperbilirubinemia and percutaneous needle biopsy of the liver was also carried out in 59 patients to evaluate differences in liver pathology between GS and CNS-II." (PMID 29137095, 2017). "Short HO-1 promoter GT-repeat and GA at nt211 in UGT1A1 were at greater risk of hyperbilirubinemia." (PMID 27557546, 2016). "Interestingly, even though sorafenib is mainly metabolized by UGT1A9, it was demonstrated that the AUC of sorafenib was twice higher in patients with UGT1A1 variants or with hyperbilirubinemia." (PMID 27822186, 2016). "In addition, other gene variants – including heme oxygenase (HO)-1, hepatic solute carrier organic anion transporter 1B1 (SLCO1B1), and UDP-glucuronosyltransferase 1A1 (UGT1A1)—have been reported as risk factors of neonatal hyperbilirubinemia." (PMID 27557546, 2016). "Therefore we conclude that the UGT1A1*6 variant is only a risk factor for hyperbilirubinemia, with heterogeneity in phenotypes observed among individuals." (PMID 26107955, 2015). "UGT1A1-catalyzed glucuronidation is a rate-limiting reaction in bilirubin metabolism in humans; therefore, genetic polymorphism in the UGT1A1 gene can cause hyperbilirubinemia." (PMID 26147428, 2015). "The pooled data of the two studies from India that explored the contribution of UGT1A1 polymorphisms to the risk of neonatal hyperbilirubinemia showed significant cumulative risk estimate (OR, 4.92; 95% CI, 1.30–18.62, p = 0.019), with high heterogeneity (I2 = 74.0%)." (PMID 25675342, 2015). "Apart from classical TA repeat insertion, recent data have also shown that other common variants can contribute to mild hyperbilirubinemia in an additive manner with TA repeat, in particular rs4124874 and a coding SNP in UGT1A1 rs4148323 (G71R), with an influence on expression levels of UGT1A1." (PMID 26413716, 2015). "Some studies suggest that hyperbilirubinemia may be exacerbated in ethnic African populations where UGT1A1 polymorphisms associated with Gilbert’s syndrome are prevalent, especially with concurrent G-6-PD deficiency." (PMID 25675342, 2015). "Additionally, two tag SNPs, rs6717546 (g+914a) and rs6719561 (t+2558c), both located in the 3′ of UGT1A1, were associated with neonatal breast-fed hyperbilirubinemia too." (PMID 25102181, 2014). "In Japanese individuals with unexplained jaundice, a potential UGT1A1 mutation should be considered in the differential diagnosis, and preterm infants with this polymorphism may be at risk for late onset hyperbilirubinemia." (PMID 23388413, 2013). "For example, the activity of UGT1A1 conjugation in the tight control of bilirubin metabolism has established the importance of UGT1A1 genetic polymorphisms in the pathogenesis of toxic hyperbilirubinemias such as the Crigler-Najjar and Gilbert's syndromes in humans." (PMID 19680455, 2009). "Furthermore, patients with a UGT1A1 promoter polymorphism are more likely to develop hyperbilirubinemia after treatment with the anti-retroviral protease inhibitor atazanavir." (PMID 18710488, 2008).
Hyperbilirubinemia (continued). "Inhibition of UGT1A1 leads to hyperbilirubinemia, which may cause damage to the nerve and liver." (PMID 39309689, 2024). "The co-expression OATP1B1 polymorphism with UGT1A1 variants could result in diminished hepatic bilirubin uptake with decreased hepatic bilirubin conjugation, impairing bilirubin clearance thus increasing hyperbilirubinemia." (PMID 37508669, 2023). "Therefore, instead of using biochemical phenotyping, in this study, we investigated the association between GS and HBV infection outcomes using UGT1A1 genotyping and explored the therapeutic potential of hyperbilirubinemia against HBV infection for the first time." (PMID 38028601, 2023). "Therefore, the authors speculated that different expression levels of UGT1A1 in G71R mutation and UGT1A1 wild-type might be the mechanism underlying the development of neonatal hyperbilirubinemia." (PMID 35415244, 2022). "Our findings show that hyperbilirubinemia is associated with reduced fat mass, and increased hepatic mitochondrial biogenesis, specifically in female animals, suggesting a dual role of elevated bilirubin and reduced UGT1A1 function on adiposity and body composition." (PMID 33762933, 2021). "Mild unconjugated hyperbilirubinemia, known as “Gilbert’s syndrome”, has a prevalence of 5–10% in Caucasians and is associated with a polymorphism of the 5′ end of the UGT1A1 gene promoter, a homozygous insertion of thymine–adenine (TA) pairs (genotype UGT1A1*28/*28)." (PMID 32987702, 2020). "Moreover, the compound heterozygous UGT1A1 variant has also been reported in GS, suggesting that UGT1A1 variant may have a cumulative effect on unconjugated hyperbilirubinemia." (PMID 31737051, 2019). "Notably, hyperbilirubinemia caused by UGT1A1 gene polymorphisms and locus-specific mutations in the HO-1 gene should be considered during the diagnosis and treatment of hyperbilirubinemic infants with unknown causes." (PMID 30298137, 2018). "In addition, our findings indicated that the G211A variant of the UGT1A1 gene was a risk factor for neonatal hyperbilirubinemia in Fujian, Southeastern China, and the AA homozygous mutant newborns had a higher risk of hyperbilirubinemia than heterozygous mutant newborns." (PMID 30298137, 2018). "Genetic variation in the uridine diphosphate glucuronosyltransferase 1A1 gene (UGT1A1) is the major cause of hyperbilirubinemia and is therefore suitable for exploring whether elevated bilirubin levels is a direct cause of reduced risk of NAFLD using a Mendelian randomization approach." (PMID 30619479, 2018). "Therefore, the UGT1A1 211 G>A mutation is a risk factor for neonatal hyperbilirubinemia among both term and late pre-term infants in Chongqing, China, which could be a common cause of severe jaundice with unknown cause." (PMID 28662083, 2017). "Genetic defects in the human UGT1A1 gene are associated with unconjugated hyperbilirubinemia, which can be either asymptomatic as in individuals with Gilbert syndrome or severe as in the case of Crigler-Najjar syndrome types I and II, depending on the remaining UGT1A1 activity." (PMID 25147562, 2014). "Moreover, nilotinib is not a substrate for uridine diphosphate glucuronosyltransferase 1A1 (UGT1A1) enzymes, but an inhibitor of human UGT1A1 in vitro, and CML patients with the UGT1A1*28 polymorphism show an increased risk of nilotinib-induced hyperbilirubinemia." (PMID 24650752, 2014). "The pathogenesis is unconjugated hyperbilirubinemia due to reduced hepatic UDP-glucuronosyltransferase 1A1 (UGT1A1) activity." (PMID 41973709, 2026). "Crigler-Najjar syndrome type I (CN-I) is a rare autosomal recessive disorder caused by mutations in the UGT1A1 gene, leading to a deficiency of bilirubin-UDP-glucuronosyltransferase and resulting in severe unconjugated hyperbilirubinemia." (PMID 41523389, 2025). "UGT1A1 gene mutation can lead to the reduction or complete disappearance of UGT1A1 activity, eventually resulting in hyperbilirubinemia." (PMID 39981091, 2025).